CEACAM1 (CEA cell adhesion molecule 1)
Diseases named in the same sentence as CEACAM1 in open-access papers (continued):
Sharing a sentence is not in itself a finding about the gene and the disease.
tumor (244 papers, 2005 to 2026). "In SARC, elevated CEACAM1 expression was significantly associated with favorable clinical outcomes and characterized by an immune-enriched tumor microenvironment." (PMID 42077470, 2026). "Quantitation of the median levels of CEACAM1 on cells associated with metacluster C58771 revealed significantly elevated levels in the treatment-resistant tumor samples compared to the healthy donor control samples." (PMID 38956268, 2024). "The first is that in both cases CEACAM1 expression was increased in the tumor-associated cells of the treatment-naive and -resistant patients." (PMID 38956268, 2024). "T cell exhaustion, a known mechanism widely described to inhibit CD8+ T cell proliferation and their capability to kill tumor cells, has been linked to several genes highly expressed in various tumor tissues like CEACAM1 and SIRT7." (PMID 39117605, 2024). "Further, the highest CEACAM1 and PD-L1 levels were observed in the treatment-resistant tumors; CEACAM1 and PD-L1 levels were also elevated on the treatment-naive tumor-associated monocytic cells relative to the healthy donors." (PMID 38956268, 2024). "And the results also showed that CEACAM1 expression was associated with tumor size status (P = 0.002), metastasis status (P = 0.007), histologic grade (P < 0.001), pathologic stage (P = 0.001), and gender (P < 0.001)." (PMID 36712923, 2023). "The data suggest that CEACAM1 functions as a tumor suppressor in the early stages of tumorigenesis, as knockout or loss of CEACAM1 is associated with increased tumorigenic potential." (PMID 36741860, 2023). "The inhibition of NK functions, in addition to the mechanism associated with TIM-3, occurs during the interaction of two CEACAM1 molecules localized on the activated NK and on the tumor cell." (PMID 36140182, 2022). "In fact, we demonstrate that the TIM3 ligands galectin 9, PtdSer, and CEACAM1 tend to be linked to tumor grade; analysis of GlioVis data showed that their expression was highest in GBM." (PMID 33800561, 2021). "In univariate analyses, the presence of CEACAM1+ TILs in tumor tissues was linked to poor overall survival and disease-free survival (POS = 0.015, PDFS = 0.011)." (PMID 34368221, 2021). "A prior study has shown the association between the loss of CEACAM1 expression in tumor tissue and aggressive tumor behavior." (PMID 34837908, 2021). "Some studies have associated CEACAM-1 with aggressive tumour behaviour (i.e. high grade, advanced stage, metastasis and survival) in different human cancers." (PMID 33238953, 2020). "Decreased expression, down regulation or loss of CEACAM-1 expression in tumour cells has previously been reported." (PMID 33238953, 2020). "CEACAM1 protein was implicated in cell proliferation, apoptosis, angiogenesis and immune-regulation during tumor development." (PMID 32414367, 2020). "NUGC3 cells with loss of CEACAM1 had most invasiveness, worst lumen formation, and more tumor growth." (PMID 31481751, 2019). "The expression of CEACAM1 on tumor cells has been implicated as a prognostic factor while different associations have been observed depending on tumor types and the stage of the cancer." (PMID 30349641, 2018). "In this study, CEACAM1 expression on tumor cells and increased neutrophils infiltration were associated." (PMID 30406153, 2018). "Congruently, loss of CEACAM1 expression is significantly associated with tumor size, multiplicity of tumor nodules, formation of satellite nodules, and capsular and vascular invasion (portal vein), all of which are adverse to patient survival." (PMID 30314283, 2018). "Consistently, loss of CEACAM1 expression is more frequently observed in tumor HCC specimens with Edmondson-Steiner-Grades III or IV, compared to Edmondson-Steiner Grades I and II." (PMID 30314283, 2018). "As a tumor suppressor, its loss promotes early tumor development by reducing CEACAM1-mediated growth inhibitory signaling." (PMID 30050594, 2018).
tumor (continued). "During tumor development, CEACAM1 is associated with tumor cell proliferation, apoptosis, angiogenesis, invasion and migration." (PMID 27074014, 2016). "The diagnostic and prognostic values of serum soluble CEACAM1 in cancer patients is receiving scrutiny; CEACAM1 as a diagnostic tumor marker has been reported for several different cancer types." (PMID 27074014, 2016). "Using Spearman’s rho coefficient test analysis, we found that the density of neutrophils was positively associated with CEACAM1 expression on tumor cells (P = 0.002)." (PMID 24587171, 2014). "Aberrant CEACAM1 expression is associated with tumour progression and has been found in a variety of human malignancies." (PMID 23885995, 2013). "According to previous reports, serum CEACAM1 is dysregulated in different malignant tumours and associated with tumour progression." (PMID 23885995, 2013). "In previous investigations, we focused on the structural and functional determinants of tumor suppression mediated by CEACAM1-4L, one of two major splice variants expressed in rat liver." (PMID 22235309, 2012). "ICAM-2 and CEACAM1 are also similar in that their association with the actin cytoskeleton and their suppression of tumor growth or metastasis (for CEAMCAM1 or ICAM-2, respectively) depend on an intact intracellular domain [37 and data herein]." (PMID 18978946, 2008). "Further, the 4 CEACAM1+ metaclusters mapped to distinct locations within the viSNE coordinates and represented approximately 22–24% of the tumor-associated CD8+ T cells that were mostly derived from metaclusters M3 and M9 with fewer contributions from M1 and M2." (PMID 38956268, 2024). "Our studies together suggest that CEACAM1 expression is predominantly associated with and may suppress memory-related B cell responses in the tumor microenvironment." (PMID 38956268, 2024). "Thus, CEACAM1 and PD-L1 were upregulated on tumor-associated DC with the highest levels found in treatment resistance." (PMID 38956268, 2024). "In addition, cell adhesion molecules and neuroative ligand-receptor interactions were involved in tumor progression, as indicated by the fact that CEACAM1, a cell adhesion molecule, was associated with tumor angiogenesis and LYM." (PMID 38638428, 2024). "Furthermore, CEACAM1 deficiency enhanced the permeability of tumor vasculature due to increased basal Akt kinase and endothelial nitric oxide synthase (eNOS) activities." (PMID 38077351, 2023). "CEACAM1 expressing tumor cells caused intracellular retention of various NKG2D ligands." (PMID 30871206, 2019). "Moreover, the functional effects triggered by these distinct CEACAM1 splice variants seem to act differently in different tumor identities." (PMID 30871206, 2019). "Reduced growth of CT26 tumor cells was observed in CEACAM1 deficient mice." (PMID 30349641, 2018). "In vitro analysis revealed that forced expression of CEACAM1 caused a significant G0/G1 phase arrest, with enhanced cell–matrix adhesion and increased cell invasion, resulting in diminished tumor growth and increased tumor invasiveness when applied to a xenograft mouse model." (PMID 30406153, 2018). "This suggests that CEACAM1 association with and activation of SFKs may promote tumor cell growth as another explanation for the divergent roles ascribed to CEACAM1 in malignancy." (PMID 28332308, 2017). "CEACAM1 expression on tumor cells was associated with more neutrophils infiltration." (PMID 24587171, 2014). "It reinforced the hypothesis that the tumour suppressive or oncogenic effects of CEACAM1 were splice variant-dependent." (PMID 23885995, 2013). "For example, CEACAM5 expressed by tumor cells can interact with CEACAM1 expressed by NK cells and lead to the inhibition of NK cell-mediated tumor target cell killing." (PMID 41283511, 2025).
tumor (continued). "TIM-3 interacts with four distinct ligands: galectin-9, phosphatidylserine (PtdSer), high-mobility group protein B1 (HMGB1), and carcinoembryonic antigen-related cell adhesion molecule-1 (CEACAM-1), all of which are implicated in tumor progression." (PMID 40565041, 2025). "CEACAM1 not only suppresses the inflammatory response but also initiates extracellular matrix remodeling during tumor development." (PMID 40046057, 2025). "Within tumor microenvironments, Exos shuttle oncogenic cargo (e.g., β‐catenin, CEACAM1, HER2, Melan‐A/MART‐1, LMP1) bidirectionally between malignant cells and stromal compartments, reprogramming recipient cells through horizontal oncogene transfer." (PMID 40910352, 2025). "In contrast, mice that received CEACAM1-depleted tumor cells had delayed bioluminescence signals and a median survival of 60 days." (PMID 40436855, 2025). "Consistent with the in vitro results, CEACAM1 blockade treatment in a tumor xenograft mouse model resulted in a favorable decrease in tumor size." (PMID 40604306, 2025). "The high binding affinity of CbpF/CEACAM1 suggests a role of CbpF not only in immune suppression, but possibly also in Fn tumor colonization." (PMID 40198705, 2025). "Another study revealed that CEACAM1+ Tregs preferentially accumulate in tumor sites, are highly activated, and exhibit strong suppressive capacity." (PMID 40703514, 2025). "Blocking the expression of CEACAM1 on the surface of EpCAMhigh cells using CEACAM1 antibodies can increase the toxicity of NK cells and promote tumour regression." (PMID 40665579, 2025). "This response pattern aligns with the identification of CEACAM1+ Tregs in a tumor microenvironment dominated by activated Tregs." (PMID 40773294, 2025). "Of the 12 chemokines compared, IL-6, Angiopoietin-2, IL-8, and CEACAM-1 were significantly higher in the tumor group (IL-6: p = 0.02, Angiopoietin-2: p = 0.007, IL-8: p = 0.003, CEACAM-1: p = 0.001)." (PMID 39652104, 2025). "Carcinoembryonic antigen-related cell adhesion molecule 1 (CEACAM1) binds to CEACAM1 on natural killer cells and Tim3 on T cells, thereby suppressing the body’s anti-tumor immune response." (PMID 40519270, 2025). "The accumulation of CEACAM1+ Tregs correlates with tumor progression; notably, their depletion enhances tumor-infiltrating lymphocyte (TIL) function and potentiates the therapeutic efficacy of anti-programmed death-1 (PD-1) therapy." (PMID 40703514, 2025). "CEACAM1 thus marked unique types of immature and mature DC that were expanded within the tumor tissues and overlapped with PD1 and PD-L1 expression; the highest levels of CEACAM1 expression were present in treatment-resistant disease." (PMID 38956268, 2024). "Histograms displaying the median CEACAM1 expression levels confirmed this and showed that the highest levels were present in the treatment-resistant tumor samples." (PMID 38956268, 2024). "DIA 12.3 exhibited some cross-reactivity to CEACAM5, a tumor marker with high sequence homology to the N-terminal domain of CEACAM1." (PMID 38346003, 2024). "Among BRD4 targets, we also identified CEACAM1, which was reported to inhibit NK-mediated cytolysis of tumor cells and KLRG1, a negative regulator of CD8+ lymphocytes and NK cells." (PMID 38519469, 2024). "Widely recognized for its role in monitoring relapse and chemotherapy responses in CRC patients, CEACAM1 also acts as a regulator of apoptosis in colon cells, functioning as a tumor suppressor." (PMID 38646539, 2024). "Despite the paradoxical trends of CEACAM1 expression in different tumors, CEACAM1 has been verified to play a pivotal role during tumor development." (PMID 39513107, 2024). "CEACAM1 is present on distinct types of cells that are unique to the tumor microenvironment and exhibit expression levels that are highest in treatment resistance; this includes tumor-infiltrating CD8+ T cells." (PMID 38956268, 2024).
tumor (continued). "CEACAM1, PD1, and PD-L1 expression were observed at variable levels on all the major immune cell types detected in the tumor-associated PBMC and/or tumor tissue." (PMID 38956268, 2024). "CEACAM1 and PD-L1 levels were increased in the treatment-naive and -resistant tumor samples relative to that observed in PBMC; the levels of PD1 expression were also increased in the tumor-associated PBMC, although not significantly, as was CEACAM1." (PMID 38956268, 2024). "Citrus analysis thus confirmed CEACAM1 expression in treatment-naive and -resistant tumor tissue with the highest levels in the latter." (PMID 38956268, 2024). "Similar to the gene expression analysis of BM CD11b+ cells isolated from Egfl6 mice, CD11b+ cells isolated from 2F8c-Egfl6 tumors displayed higher IL10, Cxcl2, Clec5a, and Ceacam1 gene expression compared with tumor controls." (PMID 39312740, 2024). "Here, the homophilic interaction of CEACAM1 displays an inhibitory effect, preventing NK‐mediated tumour killing and, therefore, permitting tumour growth." (PMID 39674881, 2024). "Together, these studies reveal overlapping CEACAM1, PD1, and PD-L1 expression in the tumor-associated samples." (PMID 38956268, 2024). "An overlay of the scaled expression of CEACAM1 on the viSNE map and its quantification showed significantly increased CEACAM1 levels in the treatment-resistant tumor samples relative to expression in healthy donor controls." (PMID 38956268, 2024). "NKG2D engagement typically leads to cytolysis of target cells, except when both NKs and target cells (e.g. tumour cells) express CEACAM1." (PMID 39674881, 2024). "As a carcinoembryonic antigen (CEA) and a member of the immunoglobulin superfamily, CEACAM1 plays an essential role in the development of ECs, crucial for the formation of tumor vasculature and lymphatics." (PMID 39232806, 2024). "Starting from a scFv, a fully human intact anti-CEACAM1 (DIA 12.3) that recognizes the N-terminal domain of CEACAM1 was developed and shown to bind CEACAM1 positive tumor cells and enhanced NK cell killing of CEACAM1 positive targets." (PMID 38346003, 2024). "There is a close relationship between abnormal alterations in CEACAM1 expression and tumor progression and prognosis." (PMID 39513107, 2024). "Interactions of Tim-3 with the membrane-bound or soluble CEACAM1 and/or galectin-1 produced by tumor cells led to the inhibition of NK-cell-mediated tumor cell killing independent of MHC class I status." (PMID 39457710, 2024). "Multivariate cox regression analysis also showed a significant relationship between CEACAM1 expression and the status of tumor presence or absence in BLBC (p < 0.0001)." (PMID 39513107, 2024). "We overlaid CEACAM1, PD1, and PD-L1 expression on the DC-associated viSNE coordinates and found that these were expressed and mapped together in several of the distinct tumor-associated islands." (PMID 38956268, 2024). "Further, the median CEACAM1 expression levels on all these Citrus metaclusters were significantly increased in the treatment-resistant, relative to treatment-naive, tumor samples." (PMID 38956268, 2024). "CEACAM1, 5, and 6 have shown their importance in gastrointestinal pathologies as they are closely involved with immune regulation, tumorigenesis, tumor suppression, and pathogen binding." (PMID 36741860, 2023). "Due to an observed downregulation of CEACAM1 in early CRC, CEACAM1 was originally suggested to be a tumor suppressor." (PMID 38077351, 2023). "CEACAM1 is expressed on various immune cells, tumor cells, and other cells to exert various biological functions." (PMID 36712923, 2023). "(F) RTqPCR quantification of Ceacam1 expression in sorted tumour cells from athymic nude and NSG mice." (PMID 36656749, 2023). "The majority of these studies shows enhanced CEACAM1 expression with progressive tumor stage and/or metastasis." (PMID 38077351, 2023).
tumor (continued). "It is also expressed on the surface of several immune cell subsets, including macrophages, T lymphocytes, and NK cells, where homophilic interactions with the CEACAM1+ tumour cells abrogate NK-mediated cytotoxicity." (PMID 36656749, 2023). "CEACAM1 plays a role in adhesion and in pathways related to survival, differentiation as well as growth and it has been suggested to act as a tumor suppressor." (PMID 37313172, 2023). "SOX10 knockout in immune-competent models leads to reduced expression of immune checkpoint proteins HVEM and CEACAM1, facilitating tumor growth." (PMID 38132479, 2023). "Crosslinking of CEACAM1 on the cell surface of tumor cells using monoclonal antibodies specific for CEACAM1 leads to apoptosis." (PMID 36741860, 2023). "CEACAM1 expression, a component of NET webs, is associated with T-cell exhaustion and resistance to tumor infiltrating lymphocytes immunotherapy in melanoma patients." (PMID 37143649, 2023). "Similar to the inhibitory signaling mode of PD-1, CEACAM1 represses the anti-tumor activity of T cells by dephosphorylating the downstream kinases of T cell receptor signaling." (PMID 37575253, 2023). "We then obtained the tumour tissues and performed immunohistochemistry to detect the expression of CEACAM1 on murine intracranial glioma cells." (PMID 36928507, 2023). "A similar inhibitory effect was observed in CRC and neck squamous cell carcinoma by trans interaction of CEACAM1 on tumor cells with TIM3 on T cells." (PMID 38077351, 2023). "Other research indicated that CEACAM1 homophilic interactions restraining multiple effector functions of tumour-infiltrating T-cells." (PMID 36928507, 2023). "Studies have shown that CEACAM1 can have multifaceted effects of immune checkpoint inhibitors and tumor markers and is an attractive target for cancer immunotherapy." (PMID 37589542, 2023). "Forced expression of CEACAM1 in thyroid cancer cells promoted cell–matrix adhesion, migration and tumor invasiveness via upregulation of cyclin dependent kinase inhibitor 1A (p21) and diminished retinoblastoma protein (Rb) phosphorylation." (PMID 38077351, 2023). "Carcinoembryonic antigen-related cell adhesion molecule 1 (CEACAM-1), an important ligand for Tim-3, is highly expressed in a variety of advanced tumor tissues." (PMID 37055849, 2023). "Although its tumor suppressive properties are evident, the role of CEACAM1 in cancer is bimodal, with many similarities to the TGF-β signaling pathway; early effects being tumor suppressive, and more invasive cancers relying on it for malignant potential." (PMID 36741860, 2023). "Bottom panels show quantification (left) and mean fluorescent intensity (MFI, right) of the Ceacam1 expressing tumour cells." (PMID 36656749, 2023). "CEACAM1 can also affect tumor immunotherapy by regulating the activation and apoptosis of immune cells." (PMID 37589542, 2023). "NEO-201 can block the interaction between CEACAM-5 expressed on tumor cells and CEACAM-1 expressed on natural killer (NK) cells to reverse CEACAM-1-dependent inhibition of NK cytotoxicity." (PMID 35804808, 2022). "Interactions between CEACAM5/6 on tumor cells and CEACAM1 on immune cells inhibit immune-mediated cytotoxicity." (PMID 35869114, 2022). "The most recently discovered ligand, CEACAM1, is a membrane protein expressed on T cells, but also other immune cells and tumor cells such as melanoma." (PMID 35464394, 2022). "Carcinoembryonic antigen-related cell adhesion molecule 1 (CEACAM1) mediates the direct interaction between tumor and immune cells as a cell-cell communication molecule." (PMID 36212177, 2022). "The evidence presented for Fn dissociating CEACAM-1 from its inhibitory effector SHP-2 is consistent with the well-established paradigm whereby microbial carcinogenesis targets tumor suppressor mechanisms." (PMID 36139097, 2022).